RAC1 (Rac family small GTPase 1)
Diseases named in the same sentence as RAC1 in open-access papers (continued):
Sharing a sentence is not in itself a finding about the gene and the disease.
retinal degeneration (4 papers, 2011 to 2022). Degeneration of the retina. "Second, the rod-specific knockdown of CDC42 did not prevent photoreceptor loss in the light-induced or inherited model of retinal degeneration—in contrast to the rod-specific ablation of RAC1, which protected rods after excessive light exposure." (PMID 22128240, 2011). "RAC1, another classical member of the small Rho GTPases, has recently been shown to have a pro-apoptotic role in light-induced retinal degeneration." (PMID 22128240, 2011). "The small GTPase RAC1 was recently shown to be a pro-apoptotic factor in the model of light-induced retinal degeneration." (PMID 22128240, 2011). "In addition, miR-96 plays an important role in Rac1 signaling pathway in a mouse model of inherited retinal degeneration." (PMID 35119588, 2022). "This suggests that the activation of Rac1 and Cdc42 pathways precedes retinal degeneration." (PMID 27775019, 2016). "To be able to directly compare the results obtained for CDC42 to the RAC1 data published recently, we used the same experimental approach as published and analyzed retinal degeneration in mice, specifically in rod photoreceptors, with a conditional Cdc42 knockdown." (PMID 22128240, 2011). "Based on our findings, it will be important to explore whether approaches that improve Rac1 regulation could be useful to improve photoreceptor survival in rd8 and, ultimately human CRB1-related retinal degenerations." (PMID 28671996, 2017). "We hypothesized that Rac1 constitutive activation following CNF1 treatment induced and increase in ROS and in retinal oxidative stress, contributing to primary photoreceptor death in our inducible model of retinal degeneration." (PMID 27775019, 2016). "Since RAC1 and CDC42 are members of the same family of proteins, and since they can have overlapping functions, we addressed the question of whether CDC42—similar to RAC1—might also influence processes involved in retinal degeneration." (PMID 22128240, 2011).
Salmonella Infections (4 papers, 2013 to 2021). Infections with bacteria of the genus SALMONELLA. "MG downregulated QS genes in Salmonella infections and suppressed the rac-1 gene of the host cells." (PMID 30286813, 2018). "RAC1 and CDC42 are major Rho GTPases during cellular Salmonella infection and their activation through Salmonella effector proteins leads to formation of filopodia and uptake of pathogens." (PMID 23826261, 2013).
skin papilloma (4 papers, 2016 to 2021). A benign papillary neoplastic growth on the skin composed of epithelial cells and a fibrous stalk. "The MT repolymerization after nocodazole treatment was shown to stimulate TIAM2, which in turn activates RAC1 on the leading edge of skin papilloma cells, stimulating actin repolymerization and membrane protrusion." (PMID 34830827, 2021). "In terms of viral carcinogenesis, RAC1 was found to facilitate HPV-8 related skin papilloma development." (PMID 35366267, 2021). "DMBA/TPA skin carcinogenesis studies in mice have shown that Rac1 is required for chemically induced skin papilloma formation." (PMID 28277539, 2017). "Rac1 has been reported to be essential for skin papilloma formation in chemical skin carcinogenesis experiments." (PMID 27506937, 2016). "In our study we identified, in addition, a role of Rac1 in the development of HPV-8 related skin papillomas in mice: inhibition of Rac1 activity or epidermis specific deletion of Rac1 led to a strong decrease in both spontaneous and UV-light induced skin papilloma formation." (PMID 27506937, 2016). "We therefore asked whether the presence of Rac1 would also be required for skin papilloma formation in a chronic UV-irradiation protocol in K14 HPV-8 mice." (PMID 27506937, 2016). "We thus present direct evidence for a so far unknown dual role of Rac1 in chronic UV-light induced skin carcinogenesis: Rac1 is required for the formation of skin papillomas but its absence facilitates the formation of SCCs in K14 HPV-8 mice." (PMID 27506937, 2016). "We followed these K14 HPV-8/Rac1-EKO mice and K14 HPV-8 mice as controls over 350 days and recorded the appearance of skin papillomas." (PMID 27506937, 2016). "To further analyze a possible co-operation of Rac1 and HPV-8 in skin papilloma formation, we generated double transgenic K14 HPV-8/K14 L61Rac1 mice expressing HPV-8 and, in addition, an activating mutant of Rac1, L61Rac1, both under the control of the K14 promoter." (PMID 27506937, 2016).
spina bifida (4 papers, 2016 to 2022). A congenital neural tube defect in which vertebrae are not fully formed. "Analysis of transverse sections through the PNP at E9.5 revealed normal-appearing dorsolateral hinge points in Grhl3Cre-Rac1 embryos, thus arguing against a neural plate bending defect as the underlying cause for the spina bifida phenotype." (PMID 27114066, 2016). "Grhl3Cre-Rac1 mutants developed spina bifida at high penetrance (79.3%) although a lower frequency of curly tail as the sole phenotype was also observed (13.8%)." (PMID 31628096, 2019). "Knocking-out Rac1 in the SE leads to open spina bifida, with the timing of onset of the defect (and, consequently, the size of the lesion) correlating with the stage at which recombination of Rac1 occurs in the SE cells." (PMID 27768516, 2018). "Most of the remaining Grhl3Cre-Rac1 embryos had cranial and/or spinal NTDs: 25% exhibited exencephaly and 89% had spina bifida." (PMID 27114066, 2016). "The size of the spina bifida lesions and the timing of failure of PNP closure in ct/ct embryos are similar to those in Pax3Cre-Rac1 embryos." (PMID 27114066, 2016). "To address the question of whether the protrusion defects observed in Pax3Cre-Rac1 embryos are indeed a cause of failure of PNP closure, rather than a consequence of that failure, we chose to analyse the cell protrusive activity in a different mouse mutant with spina bifida." (PMID 27114066, 2016). "Grhl3Cre-Rac1 mice were generated previously and found to have NTDs, including highly penetrant spina bifida, but cell protrusion analysis was not performed." (PMID 27114066, 2016).
acute leukemia (3 papers, 2017 to 2023). A clonal (malignant) hematopoietic disorder with an acute onset, affecting the bone marrow and the peripheral blood. "In conclusion, our study discloses α2β1 integrin as an important pathway of acute leukemia cell resistance to anthracycline-induced genotoxic stress through its capacity to inhibit Rac1-induced DNA damage and subsequent apoptosis." (PMID 31857649, 2019). "Finally, Rac1 signal transduction is an interesting molecular target in acute leukemia and its inhibition by pharmacological agents such as ZINC69391 and 1A-116 induces the cell death program." (PMID 29228706, 2017). "In the present work we studied the antitumoral activity of the pharmacological Rac1 inhibitors, ZINC69391 and 1A-116, in a panel of human acute leukemia cell lines, representing different levels of maturation." (PMID 29228706, 2017).
aneurysm (3 papers, 2013 to 2025). Bulging or ballooning in an area of an artery secondary to arterial wall weakening. "Rac1 is required for the assembly of NOX but overexpression has been associated with aneurysm formation." (PMID 30791562, 2019). "On the other hand, NCC-specific deletion of Rac1 results in aberrant patterning of pharyngeal arch arteries, defective outflow tract septation, and aneurysms in the vessels branching from the common arterial trunk, without impairing VSMC specification." (PMID 40456777, 2025). "This phenotype closely resembles that seen in Pinch1, Rac1 and β1 integrin conditional mutant mice; therefore, our results support that, in neural-crest-derived cells, ILK and Pinch1 act as cytoplasmic effectors of β1 integrin in a pathway that protects against aneurysms." (PMID 23744273, 2013). "Based upon published results and our own, we propose that β1 integrin, ILK, Pinch1, Rac1 and Smad3 participate in a common pathway involved in an NCC morphogenetic program during cardiovascular development that, when perturbed, results in aneurysms in the ascending aorta." (PMID 23744273, 2013).
bladder (3 papers, 2015 to 2024). "Rac1 is a valid target in several bladder pathologies, and there is now clear evidence that the protein is not “undruggable”." (PMID 35740379, 2022). "The variable response of renal Rac1 to high-sodium loading was a key mechanism that modulates the salt sensitivity of blood pressure and kidney injury." (PMID 26109460, 2015).
breast adenocarcinoma (3 papers, 2008 to 2021). "In this study we show that the Ser179Glu mutant binds strongly Tiam1, a Rac1-GEF reducing Rac1-GTP by 3-fold in MCF-7 breast adenocarcinoma cells." (PMID 29121646, 2017). "Our results unravelled a novel regulatory mechanism of the basal Rac1 activity that was mediated by SDC4 in a phosphorylation- and PDZ interaction-dependent manner in MCF-7 breast adenocarcinoma cells." (PMID 29121646, 2017). "It has been shown that over-expression of IQGAP1 enhances the capacity of human breast adenocarcinoma MCF-7 cell for transmembrane migration by up-regulating the expression active CDC42 and Rac1." (PMID 19036171, 2008).
cognitive decline (3 papers, 2010 to 2023). "It further implies the notion that Rac1 activation by RacGAP inhibition can be used as a therapeutic strategy for improving AD-associated learning deficits, considering that the onset of cognitive decline in AD occurs in adulthood." (PMID 37569255, 2023). "In addition, Rac1 plasma levels weakly correlated with the cognitive decline in AD, thus suggesting that this protein might represent a marker of AD disease progression: further investigation are mandatories to confirm these preliminary results." (PMID 30005699, 2018).
colorectal adenocarcinoma (3 papers, 2012 to 2014). The most common type of colorectal carcinoma. "Studies of the Rho GTPase family member Rac in SW620 cells, genetically modified to either overexpress or lack Rac1 expression, suggested that Rac1 also plays a major role in colorectal adenocarcinoma progression." (PMID 24279335, 2013). "A marked decrease of active Cdc42 and Rac1 correlated with the high invasive potential of the cell lines established from metastatic sites of colorectal adenocarcinoma (LoVo, SKCo1, SW620 and CoLo205)." (PMID 23144867, 2012).
diabetic cardiomyopathy (3 papers, 2019 to 2025). Diabetic cardiomyopathy is a disorder of the heart muscle in people with diabetes. "Other proposed mechanisms for increased inflammation in diabetic cardiomyopathy include oxidative stress via a Ras-related C3 botulinum toxin substrate 1 (RAC1)-mediated activation of NADPH oxidase and endoplasmic reticulum (ER) stress." (PMID 31440740, 2019).
female infertility (3 papers, 2015 to 2022). Diminished or absent ability of a female to achieve conception. "Through the AKT/NF-kappaB pathway, RAC1 is involved in inflammatory changes in endometrial tissue, which is a common cause of female infertility." (PMID 35419445, 2022). "Ablation of uterine Rac1 leads to severe female infertility." (PMID 26305333, 2015).
glaucoma (3 papers, 2020 to 2025). Increased pressure in the eyeball due to obstruction of the outflow of aqueous humor. "That is, two peaks appeared at G4d and G3w, which suggests that Rac1 may be implicated in the regulation of autophagy in glaucoma." (PMID 32913260, 2020). "Wnt signaling also activates Rac1, Racgap1, Iqgap3, and Dock2 genes in this pathway that were upregulated in three day glaucoma." (PMID 37762022, 2023). "Interfering with the Rac1/mTOR signaling pathway may provide a new strategy for treating glaucoma." (PMID 32913260, 2020).
head and neck cancer (3 papers, 2021 to 2025). A primary or metastatic malignant neoplasm affecting the head and neck. "Recently, abnormal activity of RAC1 GTPase was reported in FA-deficient head and neck cancer cells and was associated with increased migration and invasive properties." (PMID 34368842, 2021). "In addition, abnormal activity of Rac1 GTPase was reported in FA-deficient head and neck cancer cells and was associated with increased migration and invasive properties." (PMID 34368842, 2021). "As of today, the biological importance and potential druggability of RAC1 genomic aberrations remain largely underexplored in head and neck cancer." (PMID 39941730, 2025).
Hyperinsulinemia (3 papers, 2020 to 2024). An increased concentration of insulin in the blood. "During hyperinsulinemia, aberrant phosphorylation of Ras-related C3 botulinum toxin substrate 1 (Rac1) by PI3K instead of its canonical target phosphatidylinositol 4,5-bisphosphate (PIP2) also leads to NOX-4 activation and ROS release in adipocytes." (PMID 39063184, 2024). "Furthermore, in the course of IR, hyperinsulinemia makes PI3K phosphorylate Rac Family Small GTPase 1 (Rac1) protein instead of PIP2, thus potentiating activity of NOX4 and elevating ROS production." (PMID 32962281, 2020).
hypertensive nephropathy (3 papers, 2019 to 2021). Kidney damage that results from chronically elevated blood pressure; complications include glomerular damage resulting in proteinuria and hematuria. "Our previous studies have demonstrated that activation of TRPC5 channels induces Rac1 activity in podocytes, which leads to the ROS production, cytoskeletal remodeling and podocyte loss in the angiotensin II type 1 receptor transgenic and spontaneous hypertensive nephropathy rat models." (PMID 34621762, 2021).
Infertility (3 papers, 2015 to 2023). "Furthermore, a Rac1 inhibitor alleviated the testicular defects in RhoGDIα−/− mice through the Rac1/cofilin/F-actin pathway, indicating a possible molecular target for treating infertility in men." (PMID 36823181, 2023).
intestinal tumor (3 papers, 2017 to 2024). "This exon, termed exon 3b, immediately follows the switch II domain of RAC1 and was discovered by investigating RAC1 expression in human and fetal tissues, as well as intestinal tumor samples." (PMID 39001533, 2024). "Tiam1 upregulation promotes intestinal tumor formation and progression via a feedback loop; aberrant Wnt activation induces Tiam1 transcription, thereby activating Rac1." (PMID 30171257, 2019).
intracerebral hemorrhage (3 papers, 2022 to 2023). A cerebrovascular disorder characterized by bleeding into one or both cerebral hemispheres including the basal ganglia and the cerebral cortex. "In turn, this finding is consistent with the report that exogenous FGF treatment dependent on FGFR-induced activation of PI3K-Akt-Rac1 signaling inhibits RhoA activity and protects the blood-brain barrier after intracerebral hemorrhage in mice." (PMID 36969192, 2023).
malaria (3 papers, 2020 to 2026). Malaria is a serious and sometimes fatal disease caused by a parasite that commonly infects a certain type of mosquito which feeds on humans. "In the attempt to identify novel erythrocyte proteins involved in the malaria parasite invasion process, we focused our attention on the human GTPase Rac1, a member of the Rho GTPase family." (PMID 33328606, 2020). "The growing collection of Rac1 inhibitory compounds could be repurposed for malaria." (PMID 33328606, 2020). "These compounds were not active against malaria parasites, at neither sexual nor asexual stages, excluding that the antimalarial activity of the Rac1 inhibitors is due to off-target effects on CDC42." (PMID 34723630, 2022).
osteoarthritis (3 papers, 2017 to 2026). A noninflammatory degenerative joint disease occurring chiefly in older persons, characterized by degeneration of the articular cartilage, hypertrophy of bone at the margins and changes in the synovial membrane. "In addition to Rac-1 activation, IL-1β-induced activation of RhoA has been associated with several types of chronic inflammatory disorders, including osteoarthritis (OA)." (PMID 41596581, 2026). "The persistent activation of both Rac-1 and RhoA by IL-1β contributes to chronic inflammatory diseases, including osteoarthritis (OA)." (PMID 41596581, 2026). "Together, this indicates that Rac1 activation contributes to the development of osteoarthritis via facilitating cartilage matrix destruction." (PMID 27442895, 2017). "This clearly highlights the therapeutic potential of targeting Rac1 to protect against osteoarthritis." (PMID 27442895, 2017). "More recently, it was shown that downregulation of the Rac1 GAP, inositol polyphosphate 5-phosphatase OCRL-1 (OCRL1), in cartilages is responsible for the aberrant activation of Rac1 in osteoarthritis." (PMID 27442895, 2017). "Consistently, active Rac1 was detected in osteoarthritis cartilages." (PMID 27442895, 2017). "Indeed, recent in vivo evidence demonstrates that inhibition of Rac1 can help delay osteoarthritis development." (PMID 27442895, 2017).
osteopetrosis (3 papers, 2016 to 2024). Osteopetrosis, also known as marble bone disease, is a descriptive term that refers to a group of rare, heritable disorders of the skeleton characterized by increased bone density on radiographs. "Deletion of Rac1 in osteoclasts has been reported to cause osteopetrosis; its deletion severely disrupts the cytoskeleton of osteoclasts." (PMID 39201553, 2024).
osteoporosis (3 papers, 2020 to 2024). A condition of reduced bone mass, with decreased cortical thickness and a decrease in the number and size of the trabeculae of cancellous bone (but normal chemical composition), resulting in increased fracture incidence. "Although currently, there are reports about the natural product, which could play a therapeutic role in bone loss diseases (osteoporosis and osteolysis) through the regulation of Rac1/2 and Cdc42 during osteoclasts cytoskeletal structuring." (PMID 32578854, 2020). "Although currently, there have been no reports on the natural product, which could play a therapeutic role in bone loss diseases (osteoporosis and osteolysis) through the regulation of Rac1/2 and Cdc42 during osteoclasts cytoskeletal structuring." (PMID 32578854, 2020). "Furthermore, dabrafenib and vemurafenib have demonstrated modulatory effects on RAC1 gene expression, suggesting their potential therapeutic relevance for osteoporosis." (PMID 38311613, 2024). "Rac1 and STING might be involved in this process, one previous study reported that Nrf2‐specific activator inhibits NF‐κB signalling pathway by STING, and hence, Nrf2‐specific activator appeared to be a potential drug in the treatment of osteoporosis by inhibiting NF‐κB." (PMID 32871020, 2020).
pancreatitis (3 papers, 2016 to 2024). Inflammation of the pancreas. "Together with evidence that inhibiting Rac1, an upstream activator of PAK, reduces the severity of pancreatitis, these results suggest that PAK2 may be a promising therapeutic target for addressing pancreatitis-related pathophysiology in pancreatic acinar cells." (PMID 39769207, 2024).
schwannoma (3 papers, 2023 to 2024). A benign, usually encapsulated slow growing tumor composed of Schwann cells. "In patients with NF2-associated schwannoma (who typically have bilateral VS), down-regulation of Rac1 activity inhibited proliferation and induced apoptosis in schwannoma." (PMID 37048724, 2023). "Lastly, in the Schwannoma, there were 864 downregulated genes and 813 upregulated genes relative to non-tumor tissue that were associated with elastic fibers and RHO/RAC1 GTPases cycles." (PMID 36865335, 2023).
adenoma (2 papers, 2015 to 2025). A neoplasm arising from the epithelium. "A Pak3High cluster (Pak3; P21 Rac1/CDC42 activated kinase 3) was the most enriched in Smad4fl/fl (10.5%) compared to Smad4+/+ (2.5%) control adenoma." (PMID 40348815, 2025).